RNU6-1101P (RNA, U6 small nuclear 1101, pseudogene)
Gene: Small nuclear RNA gene on chromosome 3 (194,533,503 to 194,533,583, reverse strand). Ensembl gene ENSG00000252053.
Homologues: Orthologues: chimpanzee U6 (96% identical), macaque U6 (78% identical). Paralogues in human: RNU6-140P (90% identical), RNU6-1099P (88% identical), RNU6-16P (88% identical), RNU6-25P (88% identical), RNU6-29P (88% identical), RNU6-35P (88% identical), RNU6-536P (88% identical), RNU6-854P (88% identical), RNU6-1 (86% identical), RNU6-144P (86% identical), RNU6-2 (86% identical), RNU6-20P (86% identical), and 1285 more.